RITA1 (RBPJ interacting and tubulin associated 1)
Description:
Tubulin-binding protein that acts as a negative regulator of Notch signaling pathway. Shuttles between the cytoplasm and the nucleus and mediates the nuclear export of RBPJ/RBPSUH, thereby preventing the interaction between RBPJ/RBPSUH and NICD product of Notch proteins (Notch intracellular domain), leading to down-regulate Notch-mediated transcription. May play a role in neurogenesis.
Synonyms: C12orf52; RITA; FLJ14827
Tractability: Small molecule: a structure with a bound ligand is known.
Gene: Protein-coding gene on chromosome 12 (113,185,045 to 113,193,653, forward strand). Ensembl gene ENSG00000139405.
Subcellular location: Cytoplasm; Nucleus; Cytoplasm, cytoskeleton, microtubule organizing center, centrosome
Subcellular location (Human Protein Atlas): Nucleoplasm; Cytosol; Golgi apparatus; Primary cilium; Primary cilium tip
Gene Ontology:
Molecular function: protein binding; tubulin binding
Biological process: negative regulation of Notch signaling pathway; nuclear export; negative regulation of transcription by RNA polymerase II; neurogenesis; Notch signaling pathway
Cellular component: centrosome; cytoplasm; cytosol; nucleoplasm; nucleus
Genetic constraint (gnomAD): Loss-of-function variants: 18 observed, 11.72 expected, observed/expected ratio (o/e) 1.54, 90% interval 1.04 to 1.93. The upper end of that interval is the gene's LOEUF score, 1.93, which puts it in group 6 of 6, group 1 being the genes least tolerant of losing a copy. Missense variants: 330 observed, 372.01 expected, observed/expected ratio (o/e) 0.89, 90% interval 0.81 to 0.97. Synonymous variants: 145 observed, 160.21 expected, observed/expected ratio (o/e) 0.91, 90% interval 0.79 to 1.04.
Homologues: Orthologues: chimpanzee RITA1 (98% identical), macaque RITA1 (93% identical), dog RITA1 (78% identical), pig RITA1 (72% identical), guinea pig RITA1 (67% identical), rabbit RITA1 (65% identical), rat Rita1 (64% identical), mouse Rita1 (64% identical), rat Rita1l1 (54% identical), tropical clawed frog rita1 (31% identical).
Diseases named in the same sentence as RITA1 in open-access papers:
RITA1 is named in the same sentence as 1 disease in open-access papers, as found by Europe PMC text mining. Sharing a sentence is not in itself a finding about the gene and the disease. The quoted sentences say what the papers report.
bladder cancer (1 paper, 2022). "Similarly, in bladder cancer cells, overexpressed RITA1 induced degradation of RBPJ by recruiting the E3 ligase TRIM25." (PMID 36293193, 2022).